SLC26A10P (solute carrier family 26 member 10, pseudogene)
Description:
Chloride/bicarbonate exchanger.
Synonyms: formerly SLC26A10
Gene: Transcribed unitary pseudogene on chromosome 12 (57,619,527 to 57,626,036, forward strand). Ensembl gene ENSG00000135502.
Subcellular location: Membrane